FGL2 (fibrinogen like 2)
Diseases named in the same sentence as FGL2 in open-access papers (continued):
Sharing a sentence is not in itself a finding about the gene and the disease.
Lewis lung carcinoma (1 paper, 2020). "In the mouse model of Lewis lung carcinoma, FGL2 induced an activated and pro-tumorigenic phenotype of cancer-associated fibroblasts in the tumor microenvironment (TME)." (PMID 32206449, 2020).
liver steatosis (1 paper, 2020). "Fgl2 deficiency attenuated liver steatosis and inflammation in diet-induced murine models of NASH." (PMID 32863955, 2020). "To determine the contribution of fgl2 to liver steatosis in NASH, we examined fat deposition in mouse livers by oil red O staining." (PMID 32863955, 2020).
Miscarriage (1 paper, 2019). A pregnancy that ends at a stage in which the fetus is incapable of surviving on its own, defined as the spontaneous loss of a fetus before the 22th week of pregnancy. "Moreover, a number of genes identified have been implicated in miscarriage (Fgl2) and in the development of placental dysfunction in the pregnancy complication, preeclampsia (Acta2, Ngf and Nov/Ccn3)." (PMID 31241463, 2019).
nonalcoholic fatty liver disease (1 paper, 2020). "Rationale: The functions of fibrinogen-like protein 2 (fgl2) have been studied in many inflammatory and neoplastic diseases, but the role of fgl2 in nonalcoholic fatty liver disease has not yet been elucidated." (PMID 32863955, 2020).
ovarian carcinoma (1 paper, 2024). A malignant neoplasm originating from the surface ovarian epithelium. "Overall, we found that blocking FGL2 alone was insufficient to prolong survival as a novel immunotherapy for ovarian cancer." (PMID 38191799, 2024). "As the results indicate that FGL2 is not expressed in most cancer cells, but is elevated in ovarian cancer ascites fluid, sFGL2 is an immunomodulatory protein of interest in the TME." (PMID 38191799, 2024).
ovarian endometriosis (1 paper, 2021). A non-neoplastic disorder characterized by the growth of endometrial tissue in the ovaries. "An IHC analysis showed that CD32B (the receptor of FGL2) exhibited the highest levels of expression in ectopic lesions (ovarian endometriosis), lower expression levels in eutopic endometrium, and the lowest expression levels in the normal endometrium." (PMID 33893391, 2021).
Pan (1 paper, 2024). "Pan cancer analysis confirms this hypothesis that changed expression of FCGR3A and FGL2 occurs in most tumor types." (PMID 39629005, 2024).
prediabetes (1 paper, 2019). "Interestingly, however, IL-33 was directly associated with FGL2 in individuals with normoglycemia and T2D but not in those with prediabetes." (PMID 31073344, 2019). "However, IL-33 was directly correlated with fibrinogen-like protein 2 (FGL2) in individuals with normoglycemia (r = 0.48; P = 0.03; n = 21) and T2D (r = 0.3; P = 0.04; n = 47) but not in those with prediabetes." (PMID 31073344, 2019).
renal fibrosis (1 paper, 2024). A final common manifestation of a wide variety of chronic kidney diseases characterized by glomerulosclerosis and tubulointerstitial fibrosis. "In kidney fibrosis models, the expression of FGL2 increases significantly and is closely related to the pathological changes of renal fibrosis." (PMID 39629005, 2024).
type 2 diabetic nephropathy (1 paper, 2011). "We examined fgl2 expression in the glomerular and tubulointerstitial capillaries and its correlation with microthromsis in rats with streptozocin-induced type 2 diabetic nephropathy." (PMID 23554679, 2011). "In summary, this study reports the novel finding that fgl2 can act as an activator of renal microthrombi contributing to glomerular hypertension and renal ischemia, which can trigger histologic alterations in experimental type 2 diabetic nephropathy." (PMID 23554679, 2011).
tumor (66 papers, 2014 to 2026). "Vaccines incorporating a mutated form of the HCMV immediate early protein (HCMV-IE1mut) when combined with tumor-associated antigens such as Fibrinogen-like protein 2 (FGL2) have demonstrated synergistic effects in preclinical models." (PMID 41471245, 2025). "Considering the close association between FGL2 and immune-related biological activities, the potential function of FGL2 in regulating the tumor immune microenvironment was explored." (PMID 38903931, 2024). "Further analysis revealed that the FGL2 protein levels were strongly associated with the T stage and tumor grade." (PMID 38903931, 2024). "Based on our observations of increased infiltration of activated NK cells, T cells and DCs into the tumour, we focused on assessing the effects of FGL2 deficiency in the context of sFGL2 action on tumour infiltrating lymphocytes." (PMID 38191799, 2024). "By rendering the host Fgl2 deficient, we were able to isolate the impact of Fgl2 production from the tumor-specific CD8+ T cells." (PMID 38902261, 2024). "FGL2 protein belongs to the fibrinogen‐associated protein family, which plays significant roles in tumour development and the immune microenvironment of tumours." (PMID 39054581, 2024). "Our analysis revealed that FCGR3A and FGL2 expression was significantly correlated with clinical variables such as age, tumor type, WHO grade, histology, IDH-1 mutation, and 1p19q status." (PMID 39629005, 2024). "To evaluate the suitability of FGL2 as a target for T cell therapy with low risk of off-tumor on-target toxicity, we assessed the expression of FGL2 in human GBM and normal tissue arrays using FGL2 mAb-clone #4, from which the αFGL2 construct was derived." (PMID 36759517, 2023). "Lower levels of FGL2 expression have been previously associated with a worse prognosis in patients with breast cancer." (PMID 38049525, 2023). "Fgl2 deficiency resulted in significantly decreased tumor weight as well as tumor progression." (PMID 40125553, 2025). "Although initially associated with inflammatory and neoplastic diseases, emerging evidence suggests that FGL2 may also influence metabolic pathways." (PMID 40978140, 2025). "In addition, FGL2 protein has been linked to tumour progression by promoting proliferation and angiogenesis within the tumour." (PMID 39062880, 2024). "However, previous studies have focused on the impact of Fgl2 produced from regulatory T cells, macrophages and tumor-associated cells (stroma, fibroblasts) as these cell types are known cellular sources of Fgl2 that can mediate immunosuppression on T cells." (PMID 38902261, 2024). "Furthermore, the mRNA information from 2013 TCGA cohort data included in the present study suggested that FGL2 expression was upregulated in ccRCC tissues and indicated that FGL2 expression was closely associated with the expression of tumour-promoting factors such as IL17 and IL-10 in ccRCC." (PMID 28978925, 2017). "We demonstrate that tumor-derived exosomes (TEX) function as efficient carriers that deliver membrane-bound Fgl2 (mFgl2) to MDSCs." (PMID 41875310, 2026). "Genetic ablation of FcγRIIB or antibody-mediated neutralization of Fgl2 abolished this exosome-mediated immunosuppressive programming, restoring T cell activity and impairing tumor growth in vivo." (PMID 41875310, 2026). "Analysis of clinical specimens revealed that Fgl2 expression is significantly elevated in tumor tissues and inversely correlates with CD8+ T cell infiltration, while positively associating with the accumulation of FcγRIIB+ MDSCs and poor patient prognosis." (PMID 41875310, 2026). "Therein, the authors posited that Fgl2-blocking antibodies provide enhanced T cell infiltration through indirect regulation of T cells, by targeting the functionality of innate cells, tumor cells, or APCs." (PMID 40125553, 2025). "FGL2, primarily produced by tumor-infiltrating macrophages/monocytes and DCs, downregulates CD40 and CD86 on CD11+ DCs through FcγRIIB/III-mediated signaling." (PMID 41470247, 2025).
tumor (continued). "Fgl2 is robustly expressed by macrophages in 10 cancer types in humans and in 6 syngeneic tumor models in mice, underscoring the clinical relevance of Fgl2 as a therapeutic target to promote T cell activity and improve patient immunotherapeutic response." (PMID 40125553, 2025). "Upon flow analyses of the draining lymph node, spleen, and tumor of these mice on day 14, we found significantly increased frequencies of FcγRIIB+ cells among CD44hiCD8+ T cells in Fgl2–/– mice compared with WT mice." (PMID 40125553, 2025). "After tumor challenge, mice were sacrificed and Fgl2 expression of several immune cell types was measured." (PMID 40125553, 2025). "The experimental design from above was used to isolate CD11b+ cells from tumor-challenged WT or Fgl2–/– mice." (PMID 40125553, 2025). "In this work, Fgl2 was elevated systemically upon tumor challenge but was most present at the tumor, shedding light on both a local and systemic mechanism of immunosuppression that macrophages can employ." (PMID 40125553, 2025). "We observed that the CD11b+F4/80+ macrophage population robustly expressed Fgl2 in the spleen of tumor-challenged mice." (PMID 40125553, 2025). "Through analysis of a publicly available dataset of 6 syngeneic mouse tumor models, we found that macrophages expressed Fgl2 in all mouse tumor models tested, with appreciable Fgl2 expression in the B16 model compared with other tumor-infiltrating populations." (PMID 40125553, 2025). "The frequency of PD-1+, CD44hi, Ki67+, TNF+, and IFN-γ+ CD8+ T cells at the tumor were also unchanged in comparing WT versus Fgl2–/– mice." (PMID 40125553, 2025). "To determine potential effector molecules impacting the enhanced fitness of tumor-specific CD8+ T cells in Fgl2-deficient mice, we next phenotypically and functionally characterized OT-I from healthy and tumor-bearing WT versus Fgl2–/– mice." (PMID 40125553, 2025). "The decreased tumor size in Fgl2–/– mice compared with WT mice was commensurate with an increased frequency of tumor-specific OT-I CD8+ T cells at the tumor and spleen on day 14 after tumor implantation." (PMID 40125553, 2025). "Fgl2 expression was significantly increased in patients with SKCM metastasis compared with SKCM primary tumor (P = 0.458 × 10–10)." (PMID 40125553, 2025). "Additional research has demonstrated that FGL2 contributes to tumor advancement in HCC by modulating the tumor cell cycle and angiogenesis." (PMID 38816776, 2024). "Fibrinogen-like protein 2 (FGL2), a member of the fibrinogen superfamily, is mainly expressed in macrophages, neutrophils, regulatory T cells, endothelial cells, and tumor cells." (PMID 39575432, 2024). "FGL2 exhibits prothrombin activity, can initiate the clotting cascade, and potentially enhances tumor progression." (PMID 38816776, 2024). "Within tumor tissues, FGL2 can enhance fibrin deposition, act as a scaffold for angiogenesis, and stimulate ECs proliferation and migration." (PMID 38816776, 2024). "Querying scRNA-seq human cancer data shows FGL2 is produced by cells in the tumour microenvironment (TME), particularly monocytes and macrophages as well as T cells and dendritic cells (DCs), while cancer cells have minimal expression of FGL2." (PMID 38191799, 2024). "Here we report that tumor-infiltrating antigen-specific PD-1+ TCF-1− CD8+ T cells express the immunosuppressive cytokine Fgl2." (PMID 38902261, 2024). "Herein, we further examined the expression of FGL2 in different types of tumours, identified its cellular targets, and explored its potential as a therapeutic target." (PMID 38191799, 2024). "It has been confirmed in mouse and human tumor models that inhibitory regulation of the Fgl2/FcγRIIB axis can effectively rescue disabled antigen-specific CD8+ T cells." (PMID 39342365, 2024). "Depletion of FGL2 diminishes the accumulation of granulocytic MDSCs and boosts the anti-tumor response of CD8+ T cells." (PMID 38816776, 2024).
tumor (continued). "In our scRNA-seq analysis of T cells from spontaneous murine tumor models, we found exhausted and regulatory-like T cells, including Cd8+Fgl2+Il2rb+ cells." (PMID 38888968, 2024). "Meanwhile, Fgl2 supports the suppression of the anti-tumor reactivity of CD8+ T cells by inducing caspase 3/7-mediated apoptosis through interaction with FcγRIIB." (PMID 39342365, 2024). "Results indicated that deletion of Fgl2 from tumor-specific OT-I CD8+ T cells significantly increased both the frequency and cell count of FcγRIIB+ CD8+ OT-I in the draining lymph node." (PMID 38902261, 2024). "Gene co-expression network analysis suggested that FCGR3A, FGL2, and their co-expressed genes were involved in inflammatory activities and tumor-related signaling pathways." (PMID 39629005, 2024). "FGL2, a member of the thrombospondin family, plays an essential role in regulating the activity of immune cells and tumor cells in GBM." (PMID 36313679, 2022). "This review discusses the immunosuppressive role of FGL2 in the GBM tumor microenvironment and its ability to promote malignant tumor progression while considering FGL2-targeted therapeutic strategies." (PMID 36313679, 2022). "Expression of the FGL2 protein was next investigated using immunohistochemistry on a cancer tissue microarray that consisted of 36 human tumour types originating from 598 individuals." (PMID 35029030, 2022). "The xenograft tumours derived from the A431 cells with stable silencing of Fgl2 expression had lower volumes and grew more slowly than the tumours derived from the control cells." (PMID 34975313, 2022). "The correlation of FGL2 expression with enhanced phosphorylation of ERK and JNK strongly suggests that FGL2 plays an important role in tumor growth in HCC by regulating the activation of the MAPK pathway." (PMID 36313679, 2022). "These suggest that anti-FGL2 antibody treatment can effectively prevent immunosuppression of the tumor microenvironment." (PMID 36313679, 2022). "In GBM, tumor cells generated fibrinogen-like protein 2 (FGL2), which interfered with GM-CSF signaling, inhibiting the activation of CD103+ cDC1s, decreasing the CD8+ T-cell response, and allowing the tumor to escape immune surveillance." (PMID 35269652, 2022). "Stable downregulation of FGL2 expression in the FGL2 knockdown HCCLM6 cell line was found to result in delayed tumor growth and reduced angiogenesis, along with decreased VEGF I and L-8 expression." (PMID 36313679, 2022). "FGL2, encoding fibrinogen-like protein 2, and HLA-E, encoding MHC class I antigen E, were significantly differentially expressed in tumor tissues; however, their expression levels were comparable at different stages of ccRCC." (PMID 35127943, 2022). "FGL2 is a member of the fibrinogen superfamily, which plays an immunosuppressive factor in the tumor microenvironment." (PMID 35860577, 2022). "FGL2 has been found to enhance tumour cell proliferation, promote the coagulation cascade and induce angiogenesis." (PMID 35029030, 2022). "Fibrinogen-like protein 2 (FGL2) is involved in a variety of inflammatory and tumor signaling pathways." (PMID 36387195, 2022). "To identify the effect of Fgl2 on tumour growth in vivo, we subcutaneously established mouse xenograft models using CSCC cells." (PMID 34975313, 2022). "Here, we review the role of FGL2 in brain cancer and discuss its role in immunosuppression and tumor progression." (PMID 36313679, 2022). "FGL2 expression was associated with small GIST size, low mitotic counts and low tumour‐infiltrating lymphocyte (TIL) counts." (PMID 35029030, 2022).
tumor (continued). "hFGL2 expression in HCC tumor cells promotes tumor growth and angiogenesis through activation of ERK and JNK pathways, and FGL2 protein secreted by tumor cells promotes angiogenesis and tumor growth through activation of the thrombin-dependent MAPK pathway." (PMID 36313679, 2022). "The tumor section staining displayed that the expression of FGL2 was raised in most CD57+, CD68+, CD8+ T cells, and vascular endothelial cells." (PMID 33867830, 2021). "FGL2 is principally generated by tumor cells, activated macrophages, T cells, and endothelial cells 28-31." (PMID 33867830, 2021). "FGL2 is highly expressed in various tumor tissues, and is an important determinant of tumor occurrence and progression." (PMID 33323552, 2020). "In GBM, fibrinogen-like Protein 2 (FGL2), produced by tumor cells, interfered with GM-CSF signaling, blunting the differentiation of CD103+ cDC1s and consequently, lowering the CD8+ T-cell response." (PMID 33374253, 2020). "Higher FGL2 expression in M2 macrophages was associated with greater DC and CD8+ T cell infiltration in ESCA tissues, which was notable because DCs can promote tumor metastasis by reducing CD8+ T cell cytotoxicity and increasing Treg numbers." (PMID 33323552, 2020). "GO and KEGG functional enrichment analyses and GSEA also showed that FGL2 expression was positively correlated with enhanced tumor killing." (PMID 32206449, 2020). "In the TME, FGL2 can promote the transformation of M1 macrophages into tumor-promoting M2 macrophages by inducing CD39 expression." (PMID 33323552, 2020). "FGL2 also increases the levels of tumor-infiltrating leukocytes such as CD8+ T cells in tumor microenvironment." (PMID 32206449, 2020). "Here, the authors show that FGL-2 expressed by GBM cancer cells acts by suppressing the differentiation of CD103+ DC cells required to activate the anti-tumor CD8+ T cell response via blocking GM-CSF signalling at NFKB, STAT1/5 and p38 level." (PMID 30683885, 2019). "The presence of FGL2 in tumor cells inhibited granulocyte-macrophage colony-stimulating factor (GM-CSF)-induced CD103+ DC differentiation by suppressing NF-κB, STAT1/5, and p38 activation." (PMID 30683885, 2019). "The current study puts forth the novel premise that tumor-elaborated FGL2 has a critical role in regulating CNS APCs." (PMID 30683885, 2019). "Cumulatively, the data indicate that tumor cell-expressed FGL2 serves as a critical onco-immune target." (PMID 30683885, 2019). "Cumulatively, these data indicate that the predominant cellular sources of FGL2 within the GBM are the tumor cells and GSCs." (PMID 30683885, 2019). "Fibrinogen-like protein 2 (FGL2) is a membrane-bound or secreted protein expressed by macrophages, T cells, and tumor cells that has coagulation activity or immune-suppressive functions." (PMID 30683885, 2019). "FGL2 promotes mammary tumor progression by promoting tumor angiogenesis or inducing epithelial-to-mesenchymal transition." (PMID 30683885, 2019). "Adding to these novel discoveries is the crucial finding that the presence of subtle FGL2 levels from tumor cells can significantly reduce the intensity of these CD103+ DC-inducing signals." (PMID 30683885, 2019). "Either FGL2 knockdown or intratumoral injection of an artificial microRNA targeting hFGL2 leads to a delayed proliferation of tumor cells and an inhibition of tumor growth and angiogenesis as well as improves survival in vivo." (PMID 30419833, 2018). "It was previously shown that Fgl2 can increase the percentage of M2 macrophages in the tumor microenvironment." (PMID 29441068, 2018). "In the present study, we focused on FGL2 expression in ccRCC samples and found that FGL2 expression was significantly increased in tumour tissues compared with that in peritumoural tissues." (PMID 28978925, 2017).